PELATON (plaque enriched lncRNA in atherosclerotic and inflammatory bowel macrophage regulation)
Synonyms: GCRL1; LINC01272; SMIM25
Gene: Long non-coding RNA gene on chromosome 20 (50,233,416 to 50,312,038, forward strand). Ensembl gene ENSG00000224397.
Diseases named in the same sentence as PELATON in open-access papers:
PELATON is named in the same sentence as 21 diseases in open-access papers, as found by Europe PMC text mining. Sharing a sentence is not in itself a finding about the gene and the disease. The quoted sentences say what the papers report.
gastric cancer (8 papers, 2019 to 2025). A primary or metastatic malignant neoplasm involving the stomach. "PELATON, also known as LINC01272, has been shown to regulate the epithelial mesenchymal transition process in colorectal and gastric cancers." (PMID 37980632, 2023). "The known reports showed that PELATON functions as an onco-lncRNA or a suppressor lncRNA by suppressing miRNA in colorectal cancer, gastric cancer and lung cancer." (PMID 35574340, 2022). "PELATON is upregulated in the tissues and plasma of patients with inflammatory bowel disease and gastric cancer and may serve as a potential biomarker for assessing the incidence and prognosis of acute coronary syndrome (ACS)." (PMID 40969769, 2025).
Allergy (1 paper, 2025). An allergy is an immune response or reaction to substances that are usually not harmful. "The allergy levels of the participants were assessed using the skin prick test (SPT), and the levels of PELATON expression in PBMCs were detected by qPCR." (PMID 41048563, 2025).
atherosclerosis (1 paper, 2020). A disease characterized by the build-up of fatty material and calcium deposition in the arterial wall resulting in partial or complete occlusion of the arterial lumen. "Additionally, normal aortic tissue, without atherosclerosis, had significantly reduced PELATON expression when compared with unstable plaque (P=0.05)." (PMID 31826651, 2020).
diabetes mellitus (1 paper, 2022). A metabolic disorder characterized by abnormally high blood sugar levels due to diminished production of insulin or insulin resistance/desensitization. "However, there was no apparent relationship between increased serum lncRNA PELATON expression and gender or diabetes mellitus." (PMID 35577857, 2022).
glioma (1 paper, 2022). A benign or malignant brain and spinal cord tumor that arises from glial cells (astrocytes, oligodendrocytes, ependymal cells).
cancer (6 papers, 2020 to 2025). A tumor composed of atypical neoplastic, often pleomorphic cells that invade other tissues. "The RNAs with significantly higher expression levels in cancer tissues than in normal tissues include PELATON, INSL4, PSG1, PSG4." (PMID 35454778, 2022).
PELATON also shares sentences with these, for which no sentence is quoted: tumor (5 papers); inflammatory bowel disease (3); colorectal cancer (2); lung carcinoma (2); acute coronary syndrome (1); autoimmune disease (1); breast carcinoma (1); Crohn disease (1); glioblastoma (1); hepatoma (1); Hypertension (1); infection (1); leishmaniasis (1); Obesity (1); prostate carcinoma (1).